DOK1 (docking protein 1)
Description:
DOK proteins are enzymatically inert adaptor or scaffolding proteins. They provide a docking platform for the assembly of multimolecular signaling complexes. DOK1 appears to be a negative regulator of the insulin signaling pathway. Modulates integrin activation by competing with talin for the same binding site on ITGB3.
Synonyms: p62dok; pp62
Tractability: PROTAC: ubiquitination databases record sites on it; its protein half-life has been measured.
Gene: Protein-coding gene on chromosome 2 (74,548,875 to 74,557,554, forward strand). Ensembl gene ENSG00000115325.
Subcellular location: Cytoplasm (Isoform 1); Nucleus; Cytoplasm, perinuclear region (Isoform 3)
Subcellular location (Human Protein Atlas): Cytosol
Pathways (Reactome):
Developmental Biology: RET signaling
Signal Transduction: PTK6 Regulates RTKs and Their Effectors AKT1 and DOK1
Gene Ontology:
Molecular function: protein binding; signaling adaptor activity
Biological process: cell surface receptor protein tyrosine kinase signaling pathway; cell surface receptor signaling pathway; Ras protein signal transduction; signal transduction
Cellular component: cytosol; nucleus; cytoplasm; perinuclear region of cytoplasm
Genetic constraint (gnomAD): Loss-of-function variants: 17 observed, 34.46 expected, observed/expected ratio (o/e) 0.49, 90% interval 0.34 to 0.74. The upper end of that interval is the gene's LOEUF score, 0.74, which puts it in group 3 of 6, group 1 being the genes least tolerant of losing a copy. Missense variants: 591 observed, 657 expected, observed/expected ratio (o/e) 0.9, 90% interval 0.84 to 0.96. Synonymous variants: 250 observed, 277.61 expected, observed/expected ratio (o/e) 0.9, 90% interval 0.81 to 1.
Homologues: Orthologues: chimpanzee DOK1 (99% identical), macaque DOK1 (92% identical), pig DOK1 (89% identical), rabbit DOK1 (89% identical), dog DOK1 (88% identical), guinea pig DOK1 (86% identical), rat Dok1 (84% identical), mouse Dok1 (84% identical), zebrafish dok1a (28% identical), Drosophila melanogaster Dok (21% identical), Drosophila melanogaster CG13398 (18% identical), Caenorhabditis elegans rog-1 (17% identical). Paralogues in human: DOK2 (30% identical), DOK3 (28% identical), DOK5 (16% identical), DOK6 (16% identical), DOK4 (16% identical), FRS2 (15% identical), FRS3 (14% identical).
Diseases named in the same sentence as DOK1 in open-access papers:
DOK1 is named in the same sentence as 45 diseases in open-access papers, as found by Europe PMC text mining. Sharing a sentence is not in itself a finding about the gene and the disease. The quoted sentences say what the papers report.
breast carcinoma (5 papers, 2014 to 2025). "Using proteomics approaches, we uncovered Cofilin as a component of the phosphorylated integrin-Dok1 complex and linked this axis to effective invadopodia formation, a process supporting breast cancer invasion." (PMID 40419795, 2025). "All-trans retinoic acid, an endogenous retinoid, has been shown to inhibit the expression of PPARγ and to enhance the expression of DOK1 as it regulates the DOK1/PPARγ pathways thus inhibiting cell proliferation in breast cancer (MCF7 cell line)." (PMID 38274206, 2023). "In breast cancer samples, the mRNA levels of DOK1 were significantly decreased in tumors compared with adjacent normal tissues and DOK1 expression was correlated between DOK1 expression and c-cerbB-2 status." (PMID 33552156, 2021). "We began by evaluating the expression of Dok1 in breast cancer cells in order to determine if there was any correlation between the expression profiles of both proteins." (PMID 24523872, 2014). "Recently, several studies of other DOK proteins such as DOK1, DOK2, and DOK6 participate in the occurrence and development of breast cancer." (PMID 33552156, 2021). "Using sub-cellular fractionation studies, on Dok1 and BRK-positive breast cancer cell lines, SKBR3 and BT20, we found that both BRK and Dok1 fractionated to the cytosolic and membrane fractions." (PMID 24523872, 2014). "We evaluated the correlation between Dok1 and BRK in breast cancer cell lines, because of the over expression of BRK in majority of breast cancer." (PMID 24523872, 2014). "Using immunoblotting analysis, we examined the expression of Dok1 and BRK in nine breast cancer cell lines and in an immortalized mammary epithelial cell line, MCF-10A, as well as in the Human Embryonic Kidney 293 (HEK 293) cells." (PMID 24523872, 2014). "Docking protein-1 (DOK1), a tumor suppressor, is frequently downregulated in human tumors such as ovarian cancer, Burkitt lymphoma, head and neck cancer (HNC), chronic lymphocytic leukemia (CLL), lung cancer, and breast cancer." (PMID 34769455, 2021). "However, it is not yet known whether the expressions of Dok1 and BRK in breast cancers are regulated epigenetically via promoter hypermethylation; although, there is evidence of BRK promoter hypomethylation in cisplatin resistant ovarian cancer cells." (PMID 24523872, 2014).
Burkitt lymphoma (4 papers, 2014 to 2024). A rare form of malignant mature B-cell non-Hodgkin lymphoma. "Similarly, the expression of DOK1 mRNA was found to be down-regulated in cell lines derived from Burkitt's lymphoma, a pathological condition associated with EBV infection." (PMID 24809689, 2014). "In our previous study, we reported that DOK1 expression is repressed in 64% of Burkitt's lymphoma cell lines through DNA hypermethylation of its promoter." (PMID 24809689, 2014). "We also showed that DOK1 gene expression is repressed in a large proportion of head and neck cancer (HNC), lung cancer and Burkitt's lymphoma, as a result of aberrant hypermethylation of its promoter region." (PMID 24809689, 2014). "Indeed several mechanisms of DOK1 inactivation have been characterized so far DOK1 expression was found to be silenced by hypermethylation of its promoter in a variety of human cancers, including, head and neck, lung, gastric and liver cancer as well as in Burkitt's lymphoma-derived cell lines." (PMID 24809689, 2014). "Dok1 was also shown to be repressed in other forms of cancer including head and neck cancer (HNC), lung, liver, and gastric cancers, likewise in Burkitt's lymphoma." (PMID 24523872, 2014). "In addition, a correlation has been reported between DOK1 aberrant hypermethylation and the presence of oncogenic viruses such as hepatitis B virus (HBV) in hepatocellular carcinoma (HCC) and Epstein-Barr virus (EBV) in Burkitt's lymphoma-derived cell lines." (PMID 24809689, 2014).
histiocytic sarcoma (4 papers, 2012 to 2024). An aggressive malignant neoplasm with a poor response to therapy, usually presenting as stage III/IV disease. "A recent report showed that mice with coincident loss of Dok-1, Dok-2 and Dok-3 genes develop highly invasive and transplantable histiocytic sarcoma endogenously, and Dok-1/2/3−/− macrophages demonstrate enhanced proliferation ability, suggesting origination of the disease in monocytic cells." (PMID 22952867, 2012). "In addition, mice with combined knockouts of Dok1, Dok2, and Dok3 developed aggressive histiocytic sarcoma or lung adenocarcinoma." (PMID 24523872, 2014). "DOK1 is considered to have antitumor roles in several cancers, such as chronic lymphocytic leukemia (CLL) 9, chronic myelogenous leukemia (CML) 8, histiocytic sarcoma 10, lung cancer 14, and epithelial ovarian cancer." (PMID 39513119, 2024).
ovarian carcinoma (4 papers, 2014 to 2024). A malignant neoplasm originating from the surface ovarian epithelium. "TOMM40L, also upregulated in our study, is upregulated in epithelial ovarian cancer cell lines overexpressing DOK1, a candidate tumor suppressor associated with cisplatin sensitivity." (PMID 32260415, 2020). "Some of the reported hypermethylated genes in ovarian cancer are BRCA1, RASSF1A, TGFBI, DOK1, RUNX3, and CAMK2N1." (PMID 38627856, 2024).
chronic lymphocytic leukemia (3 papers, 2014 to 2024). "In addition, DOK1 was found to be mutated in chronic lymphocytic leukemia (CLL)." (PMID 24809689, 2014).
gastric cancer (3 papers, 2014 to 2015). A primary or metastatic malignant neoplasm involving the stomach. "As DOK1 gene silencing was found to be related to its promoter hypermethylation in gastric cancer, it will be important to investigate whether these events are associated with the presence of EBV in these cancers and others." (PMID 24809689, 2014). "The inactivation of DOK1 through promoter methylation also occurred in liver and gastric cancers." (PMID 24809689, 2014). "RASSF1A, p14ARF, and MGMT; CHRNA3, DOK1, and GNMT; p16, hMLH1, MINT1, MINT2, MINT12, MINT25, and MINT31; APC, CDH1, MHL1, CDKN2A, CDKN2B, and RUNX3; CDH1; DKK3; PTEN; MGMT; TFPI2; CACNA2D3; PCDH10; SOX2; MAL; and COX2 were previously reported to be hypermethylated in gastric cancer." (PMID 26121593, 2015).
melanoma (3 papers, 2019 to 2024). A malignant, usually aggressive tumor composed of atypical, neoplastic melanocytes. "We also found that the overexpression of GBP4, DOK1, DDX60, and IFIH1 is correlated with better overall survival in several melanoma datasets." (PMID 34769455, 2021). "By analyzing the TCGA genomics, we also found that the gene alteration rates in the melanoma TCGA dataset were 12% for DDX60, 5% for CSNK1E, 2.8% for FGD1, 2.1% for GBP4, 4% for IFIH1, 1% for DOK1, and 0.7% for IRX3, and these alterations were not significantly correlated with mRNA expression." (PMID 34769455, 2021). "To evaluate the role of DOK1 and DOK2 depletion in physiology and effector function of CD8+ T lymphocytes and in cancer progression, we established a transgenic T cell receptor mouse model specific to melanoma antigen hgp100 (pmel-1 TCR Tg) in WT and Dok1/Dok2 DKO (double KO) mice." (PMID 38956389, 2024).
asthma (2 papers, 2012 to 2016). "In summary, these studies demonstrate that DOK-1 is a negative regulator of allergen-induced Th2 inflammation, mucus production and airway hyperresponsiveness in a murine model of asthma." (PMID 22514638, 2012). "In this study, we have demonstrated a novel regulatory role of DOK-1 in airway inflammation and physiologic responses in a murine model of asthma using lentiviral vector containing DOK-1 cDNA or DOK-1-specific ShRNA." (PMID 22514638, 2012). "Mice knock-out for Dok1 were hypersensitive to LPS showing high levels of TNFα and NO while triple KO mice (Dok1-2-3) showed spontaneous pulmonary inflammation, with hallmarks of asthma, including eosinophilia, goblet cell hyperplasia, and subepithelial fibrosis." (PMID 27169516, 2016). "The downstream of kinase (DOK)-1 is involved in the protein tyrosine kinase (PTK) pathway in mast cells, but the role of DOK-1 in the pathogenesis of asthma has not been defined." (PMID 22514638, 2012).
clear cell renal cell carcinoma (2 papers, 2024). "Bioinformatic assays indicated that the PI3K/AKT signaling pathway is a vital molecular mechanism via which the biological role of DOK1 is involved in the progression of clear cell renal cell carcinoma." (PMID 39513119, 2024).
hepatocellular carcinoma (2 papers, 2014 to 2016). A malignant tumor that arises from hepatocytes. "Indeed, a correlation between DOK1 aberrant hypermethylation and the presence of hepatitis B virus (HBV) has been reported in hepatocellular carcinoma (HCC)." (PMID 24809689, 2014).
Insulin resistance (2 papers, 2019 to 2022). Increased resistance towards insulin, that is, diminished effectiveness of insulin in reducing blood glucose levels. "In a recent study, Ha and colleagues reported that FFAs and docking protein 1 (DOK1) were associated with insulin resistance in patients with T2DM, even in the absence of obesity and prediabetes." (PMID 35056417, 2022). "They speculated that DOK1 downregulation might inhibit lipid synthesis, thus induce lipolysis and possibly worsening insulin resistance." (PMID 35056417, 2022). "There is little information on the role of Dok2 in skeletal muscle or insulin resistance, however experiments in mice lacking Dok1 or Dok2 showed enhanced expression of Erk and Akt in myeloid cells." (PMID 31266232, 2019).
liver cancer (2 papers, 2014 to 2016). An epithelial or non-epithelial malignant neoplasm that arises from the liver. "On the other hand, few data are available on the methylation profile of DOK1 in liver cancer." (PMID 27078152, 2016).
Obesity (2 papers, 2016 to 2022). Accumulation of substantial excess body fat. "For example, DOK1, the gene that encodes Docking Protein 1, was shown to mediate high-fat diet-induced adipocyte hypertrophy and obesity through modulation of PPAR-gamma phosphorylation." (PMID 27467526, 2016).
Achalasia (1 paper, 2024). A disorder of esophageal motility characterized by the inability of the lower esophageal sphincter to relax during swallowing and by inadequate or lacking peristalsis in the lower half of the body of the esophagus. "In this study, the mRNA expression levels of docking proteins 1 and 2 (DOK1 and DOK2) were analyzed and the underlying mechanisms that contribute to the onset of achalasia were investigated." (PMID 38792545, 2024). "The expression of DOK1 and DOK2 leads to the induction of IL-1β in the LES of achalasia patients, potentially leading to the esophageal motility disorder." (PMID 38792545, 2024). "DOK1 and DOK2 mRNA levels were significantly upregulated (p < 0.05) in the LES of patients with achalasia." (PMID 38792545, 2024). "DOK1 and DOK2 mRNA levels were significantly increased in the LES of patients with achalasia." (PMID 38792545, 2024). "The upregulation of DOK1 and DOK2 expression induces IL-1β expression in the LES of achalasia patients, which may contribute to the development of esophageal motility disorder." (PMID 38792545, 2024).
airway hyperresponsiveness (1 paper, 2012). "To determine the role of DOK-1 in allergen-induced physiologic response, we evaluated airway hyperresponsiveness (AHR) after methacholine challenge." (PMID 22514638, 2012).
atherosclerosis (1 paper, 2009). A disease characterized by the build-up of fatty material and calcium deposition in the arterial wall resulting in partial or complete occlusion of the arterial lumen. "In addition, it seems reasonable to speculate that the Dok-1 mediated inhibition of Erk1/2 could also predict the anti-atherogenic effects of ghrelin, given the high impact of elevated MAPK pathway in atherosclerosis." (PMID 19888469, 2009).
chronic lymphoid leukemia (1 paper, 2014). "We have reported a frameshift mutation of the DOK1 gene in chronic lymphoid leukemia (CLL) resulting in the expression of truncated DOK1 that is exclusively localized in the nucleus and loses its tumor suppressive activities, in contrast with the cytoplasmic wild type protein." (PMID 24809689, 2014).
chronic myelogenous leukemia (1 paper, 2014). "Oncogenic tyrosine kinases such as p210BCR-ABL, the causative mutation in chronic myelogenous leukemia (CML), and Src target DOK1 for ubiquitin-mediated proteasomal degradation, therefore promoting cell proliferation." (PMID 24809689, 2014).
colitis (1 paper, 2021). Inflammation of the colon. "Recently, other members of the DOK family of proteins, namely DOK1 and DOK2, have been shown to regulate colitis severity through inhibiting the expression of Th17 cytokines IL17A and IL22 in DOK1/2 double knockout mice." (PMID 34743196, 2021).
HIV-1 infection (1 paper, 2015). The type species of lentivirus and the etiologic agent of acquired immunodeficiency syndrome (AIDS). "Other pseudogene:gene pairs with modulating gene expression in early and late HIV-1 infection, but with unknown roles in viral infection, are RP11-380G5.3:DOK1 and RP11-114F3.5:THAP6." (PMID 26426037, 2015).
intestinal tumors (1 paper, 2022). "In particular, the number of relatively large (3.0 mm ≤ Φ), but not small (1.0 mm ≤ Φ < 3.0 mm), diameter tumors was significantly increased in Apc/Dok1/Dok2 mice compared with that in Apc mice, indicating that Dok-1/-2 deficiency enhances intestinal tumor growth." (PMID 36970719, 2022). "In the current study, by using ApcMin/+ mice lacking Dok-1/-2 or Dok-3, we show that Dok-1/-2 and Dok-3 play distinctive roles in growth and malignant progression of intestinal tumors." (PMID 36970719, 2022).
leukemia (1 paper, 2025). A malignant (clonal) hematologic disorder, involving hematopoietic stem cells and characterized by the presence of primitive or atypical myeloid or lymphoid cells in the bone marrow and the blood. "For instance, in our analysis, the DOK1 gene, implicated in leukemia, showed a regulatory network of 14 enhancers." (PMID 39817516, 2025).
liver disease (1 paper, 2016). "The aim of this study was to determine whether aberrant methylation of RASSF1A and DOK1 gene promoters is associated with the progression of liver disease in Brazilian patients." (PMID 27078152, 2016).
lymphoma (1 paper, 2020). A malignant (clonal) proliferation of B- lymphocytes or T- lymphocytes which involves the lymph nodes, bone marrow and/or extranodal sites. "DOK-1 usually decreases both JAK-2 and STAT-3/5 phosphorylation in lymphoma cells." (PMID 33333886, 2020).
medullary thyroid carcinoma (1 paper, 2010). "In our study, DOK1 tyrosine phosphorylation did not seem to be dependent on RET/PTC1, in contrast with DOK1 function in medullary thyroid carcinoma, where its phosphorylation was mediated by mutated RET." (PMID 20955590, 2010).
myeloid leukemia (1 paper, 2015). A clonal proliferation of myeloid cells and their precursors in the bone marrow, peripheral blood, and spleen. "The myeloid leukemia K562 cells that do not express endogenous β2 integrins were transfected with expression plasmids of integrin αL and Dok1-CFP (CFP fused to the C-terminus of Dok-1) and integrin β2-YFP wild-type or S745G/S756G or S745E/S756E." (PMID 26108885, 2015).
myeloproliferative disorder (1 paper, 2014). A clonal hematopoietic stem cell disorder, characterized by proliferation in the bone marrow of one or more of the myeloid (i.e., granulocytic, erythroid, megakaryocytic, and mast cell) lineages. "An understanding of the physiological tumor suppressor role of Dok1 emerged from mice studies, revealing a significantly accelerated onset of the p210bcr-abl-induced chronic myelogenous leukemia (CML), a myeloproliferative disorder of the hematopoietic stem cell, upon Dok1 inactivation." (PMID 24523872, 2014).
renal carcinoma (1 paper, 2019). A carcinoma arising from the epithelium of the renal parenchyma or the renal pelvis. "In our analysis DOK-1 gene expression has been shown as deregulated upon IGFR signaling which stay in accordance with data of these gene being unfavorable prognostic marker in renal cancer in The Human Protein Atlas." (PMID 30929166, 2019).
schizophrenia (1 paper, 2025). A major psychotic disorder characterized by abnormalities in the perception or expression of reality. "For instance, TF-tagged genes CRABP1, DOK1, RBM28, and C12orf65 are regulated by multiple schizophrenia-related TFs." (PMID 39905509, 2025).
triple-negative breast carcinoma (1 paper, 2014). An invasive breast carcinoma which is negative for expression of estrogen receptor (ER), progesterone receptor (PR), and human epidermal growth factor receptor 2 (HER2). "When applied to a triple-negative breast cancer (TNBC) microarray dataset, the top selected modules contain both known gene markers in TNBC and novel candidates, such as RAD51 and DOK1, which play a central role in their respective ego-networks by connecting many differentially expressed genes." (PMID 24773628, 2014).